PPARG (peroxisome proliferator activated receptor gamma)
Diseases named in the same sentence as PPARG in open-access papers (continued):
Sharing a sentence is not in itself a finding about the gene and the disease.
diabetes (continued). "PPARγ is a target of synthetic insulin sensitizers thiazolidinediones (TZDs), including pioglitazone and rosiglitazone, which were used in the treatment of type 2 diabetes mellitus (T2DM)." (PMID 30060458, 2018). "PPARγ agonists (not antagonists or inhibitors) confer benefits in diabetes and atherosclerosis, two known risk factors associated with cardiovascular disease." (PMID 29163813, 2017). "As PPARγ is involved in glucose and lipid metabolism in type 2 diabetes mellitus, it is probable that PPARγ may also play important roles in the GDM." (PMID 29371958, 2017). "The activators of PPARγ are already widely used in the treatment of diabetes mellitus." (PMID 28243251, 2017). "Pparγ agonists (TZDs) are popular drugs for the treatment of diabetes." (PMID 28393867, 2017). "Serum fetuin-A concentration was significantly associated with BMI, HOMA-IR, gender, and the Pro allele but not with the diabetes and postinfarction status, PPARγ Pro/Pro, Pro/Ala, and Ala/Ala genotypes or the Ala allele." (PMID 28781590, 2017). "The nuclear receptors peroxisome proliferator-activated receptor γ (PPARγ) and its hetero-dimerization partner retinoid X receptor α (RXRα) are considered as drug targets in the treatment of diseases like the metabolic syndrome and diabetes mellitus type 2." (PMID 29057944, 2017). "In addition, PPARγ also has been responsible for pathogenesis of several metabolic and vascular diseases including obesity, diabetes, and atherosclerosis." (PMID 28928902, 2017). "PPARγ agonists are expected to ameliorate endothelial dysfunction in diabetes." (PMID 29359008, 2017). "This Na+ retention in nephrons may contribute to the development of edema and promote secondary hypertension in patients with type 2 diabetes mellitus, as a side effect of PPARγ treatment." (PMID 27517916, 2016). "Considering the large number of diabetes patients and the popularity of PPARγ agonists (Rosiglitazone, Pioglitazone) class anti-diabetes drugs, elevated cardiac FABP4 expressions may be quite common among metabolic syndromes patients." (PMID 27294862, 2016). "Ultimately, these new knowledge will enhance our understanding of macrophage regulation, cancer microenvironment as well as PPARγ and Gpr132 biology, which may translate to a better intervention of diseases such as cancer, diabetes and inflammatory disorders." (PMID 27692066, 2016). "The peroxisome proliferator-activated receptor gamma agonist, pioglitazone (Actos®—a drug used for diabetes), shows protective effects in the brain, delays onset and severity in rodent EAE models and is used as an add-on therapy for RRMS for treatment of nerve pain." (PMID 27629829, 2016). "Peroxisome proliferator-activated receptor gamma (PPARγ) is a primary transcriptional factor that regulates adipogenesis and also operates as a known therapeutic target for type 2 diabetes mellitus and dyslipidemia to increase the lipid storage capacity of WAT." (PMID 28231178, 2016). "Elevated serum lipids are associated with exacerbation of acute pancreatitis (“lipotoxicity”) and lipoapoptosis is a prominent feature of diabetes suggesting that lipemia may contribute to diabetes in PPARγ-/F:MORE+/Cre neonates." (PMID 27505464, 2016). "In addition to blocking the renin-angiotensin system, telmisartan acts as a selective modulator of PPARγ, a central regulator of insulin and glucose metabolism and a well-known target of insulin-sensitizing drugs used to treat type 2 diabetes mellitus." (PMID 26846539, 2016). "Furthermore, PPARγ plays an important role in glucose homeostasis as an insulin-sensitizing agent, which is why agonists of PPARγ are currently used to treat diabetes." (PMID 28053991, 2016). "Therefore, the development of novel drugs for the treatment of type 2 diabetes mellitus based on PPARγ antagonists is of great importance." (PMID 25574213, 2015).
diabetes (continued). "Therefore, the screening of small molecular compounds based on PPARγ antagonists is a key strategy for the identification of novel compounds for the treatment of type 2 diabetes mellitus." (PMID 25574213, 2015). "Two coding, non-synonymous PPARG polymorphisms (rs1801282 (P12A) and rs3856806 (C141T)) have been extensively studied in diabetes, coronary artery disease, the metabolic syndrome, and non-alcoholic fatty liver disease." (PMID 25986483, 2015). "We assessed methylation of the −383 to −281 bp region of the PPARG promoter as PPARγ suppresses CYP19A1 expression in breast tissues in culture, and relative hypermethylation of this region has been associated with reduced PPARγ expression in hyperandrogenic PCOS and diabetes models." (PMID 24649863, 2014). "Here we characterize alterations in the biomechanical responses of bones from PPARβ−/− mice and identify new molecular targets, namely PPARγ and myostatin, that may contribute to the impairment of the muscle and bone functions in diabetes." (PMID 25279796, 2014). "We next determined whether the expression profile of the key lipid metabolic regulator, PPARα and PPARγ, exhibited rhythmicity in the retina and liver, and whether this rhythm was impaired in diabetes." (PMID 24736612, 2014). "Also, synthetic ligands are widely used in clinical practice – for example, fibrates (PPARα ligands) are recommended in the dyslipidemic state (hypertriglyceridemia) and thiazolidinediones (PPARγ agonists) are used in the treatment of diabetes mellitus." (PMID 24524207, 2014). "The abundance of mRNA coding for PPARγ decreased only in scWAT during diabetes." (PMID 25170835, 2014). "Whether interactions of AT1R and PPARγ play a key role in the pathogenesis of diabetes-induced atherosclerosis remains undetermined." (PMID 23374104, 2013). "Strategies that target PPARγ activation in the uterine circulation could have important therapeutic potential in treatment of pregnancies complicated by hypertension, diabetes or preeclampsia." (PMID 23888144, 2013). "The PPARG locus is of specific interest due to its link to diabetes genetics and therapy." (PMID 23754948, 2013). "Furthermore, PPARG P12A genotype showed a modest effect and is overshadowed by duration of diabetes and systolic blood pressure in the aboriginal Canadian population." (PMID 24282791, 2013). "Peroxisome proliferator-activated receptor γ (PPARγ) agonist pioglitazone previously used to treat type 2 diabetes mellitus (T2DM) has also been demonstrated to be effective in anti-inflammatory reaction and anti-oxidative stress in the animal models of AD and other neuroinflammatory diseases." (PMID 23527159, 2013). "Thus, further studies are needed to establish the safety of muraglitazar and other dual PPARγ/α agonists in other possible indications than diabetes." (PMID 23594962, 2013). "Thiazolidinediones are oral PPARγ agonists used in diabetes management." (PMID 24216701, 2013). "The PPARG locus is of specific interest due to its role in diabetes genetics and therapy." (PMID 23754948, 2013). "Therefore, many researchers have been targeting PPARγ pharmacologically for drug developments, especially concerning diabetes." (PMID 24324517, 2013). "Of the seven analyzed ‘diabetogenic’ alleles, six were more frequent in the late-onset NODAT patients than in the patients without diabetes (exception: the PPARG rs1801282 C allele)." (PMID 22569928, 2012). "For example, we have shown that treatment with the PPARγ agonist, rosiglitazone (20 mg/kg/day), attenuated glomerulosclerosis, tubulointerstitial expansion, and collagen IV deposition following the induction of streptozotocin diabetes." (PMID 22448165, 2012). "Emodin is a potent PPARγ agonist that could render it as an attractive therapeutic agent for managing diabetes mellitus which has been documented." (PMID 22649478, 2012).
diabetes (continued). "Indeed, PPARγ agonists are routinely used for the treatment of patients with diabetes or hyperglycemia and it is established that activation of PPARγ ameliorates insulin sensitivity in vivo and ex vivo." (PMID 22407012, 2012). "If rodents that possess PPARG with Pro12 consume a high-fat diet, the small-sized adipocytes accumulate more fat to change to hypertrophic adipocytes, which secrete factors that promote diabetes mellitus, such as TNFα, resistin and free fatty acids." (PMID 22937051, 2012). "Therefore, PPARγ is a major target for the treatment of various diseases, including diabetes, and has been an attractive target for new drug discovery." (PMID 22978376, 2012). "However as PKC overexpression plus decreased expression of many nuclear factors such as PPARG at 16-20w, IR deteriorates and diabetes becomes un-returnable." (PMID 21689475, 2011). "However, the independent and synergistic effect of Hcy and PPARγ in cardiac hypertrophy and matrix remodeling in diabetes is nebulous." (PMID 20828387, 2010). "A previous study showed an association between C161→T polymorphism in the PPARγ gene and a reduced risk of coronary artery disease in patients with and without diabetes in an Australian Caucasian cohort." (PMID 20334678, 2010). "The relevance of PPARgamma (peroxisome- proliferator-activated receptor gamma) as an important therapeutic target for the treatment of diabetes arises from its hypoglycaemic effects in diabetic patients and also from the critical role in the regulation of cardiovascular functions." (PMID 22615610, 2010). "However, treatment of diabetic mice with PPARγ agonist CZ, normalized the relaxation of cardiac rings, suggesting the attributed role of CZ in endothelial-myocyte recoupling in diabetes." (PMID 20613990, 2010). "Therefore PPARγ is one of the potential candidate genes for the link between diabetes mellitus and CAD." (PMID 20334678, 2010). "Thiazolidinediones (TZDs) - strong synthetic PPARγ agonists used in diabetes therapy to improve insulin sensitivity - induce weight gain whereas CLAs, natural PPARγ ligands, caused moderate weight loss in humans and in some studies reduced insulin sensitivity in an isomer specific way." (PMID 19689798, 2009). "Interestingly, we found increased methylation of the PPARγ promoter in visceral adipose tissues (VAT) of the mouse models of diabetes, compared to that observed in wild-type mice." (PMID 19589179, 2009). "That effect size would be comparable to the role of known diabetes genes including the potassium channel gene KCNJ11 E23K variant, or peroxisome proliferator activating receptor γ (PPARG) P12A variant, or more recently described variants that have required very large populations to confirm." (PMID 18366646, 2008). "Currently PPARγ is regarded as an important target for the therapies against angiogenesis-dependent pathological states including cancer and vascular complications of diabetes." (PMID 19043603, 2008). "Besides its function as an insulin sensitizerin diabetes, PPARγ was found to have a variety of roles in immunoregulation,atherosclerosis, angiogenesis, and tumorigenesis." (PMID 18784849, 2008). "PPARγ agonists may also have beneficial actions onrenal hypertrophy in models of experimental diabetes." (PMID 18288280, 2008). "We use FHS 100K SNPs in an in silico replication analysis that tests the hypothesis that SNPs in LD with published causal variants in PPARG, ABCC8, TCF7L2, CAPN10, and HNFa are associated with diabetes and related quantitative traits." (PMID 17903298, 2007). "In addition to being a therapeutic option in diabetes, PPARγ agonists are now believed to be a potential strategy for treatment of several cancers." (PMID 17584937, 2007). "However, the effects of arsenite on IUF-1 and PPARγ were contradictory in terms of diabetes development." (PMID 16675414, 2006).
diabetes (continued). "PPARγ is a member of the nuclear receptor superfamily and is activated by endogenous fatty acids as well as synthetic thiazolidinediones, such as pioglitazone and rosiglitazone, which have demonstrated clinical efficacy in treating diabetes primarily through their actions in adipose tissues." (PMID 40855678, 2025). "Moreover, at baseline, LDL/ATP-induced WAT IL-1β-secretion was associated in the direction of higher diabetes risk in subjects with high-apoB, associating negatively with 1st phase and total DI, IS, and WAT PPARG mRNA and positively with SREBP2 mRNA and android fat." (PMID 39511203, 2024). "In addition, pioglitazone, a PPAR-γ agonis widely used in clinical diabetes treatments has been shown to induce PPARγ expression and down-regulate the invasion genes snail transcription factor 1 (SLUG), MMP-9, and Vimentin, thus inhibiting the proliferation and migration of ECs and VSMCs in AVF." (PMID 39273465, 2024). "Therefore, PPARγ agonist as an insulin sensitizer is effective in the treatment of diabetes." (PMID 36874030, 2023). "Peroxisome proliferator-activated receptor gamma(PPARγ) is a nuclear receptor that plays a crucial role in the regulation of glucose and lipid metabolism, making it an essentialcomponent in the management of diabetes, metabolic syndrome, and cardiovascular diseases." (PMID 37901293, 2023). "Thus, PPARγ deacetylation appears to be able to highlight its metabolic advantages by promoting brown fat remodeling decoupling side effects, making it possible to design safer and more efficient PPARγ agonists to treat diabetes." (PMID 36551260, 2022). "Second, lack of the detail information, such as personal medication and diet, they could be the effects of early and aggressive intervention with diabetes and cardiovascular protective drugs, so it may lead to an underestimation of the relationship between PPARG Pro12 and mortality." (PMID 35265101, 2022). "Therefore, diabetes-associated targets (AKT1 and PPARγ) and two targets involved in regulating glucolipid metabolism (GSK3β and ADORA1), which have the lowest free energy binding with their compounds, were selected for molecular docking and refined by exploring the specific binding sites." (PMID 36278175, 2022). "Moreover, in adipose tissues of patients with diabetes, agonists of PPARγ increase the relative amounts of mitochondria and mitochondrial DNA copy number and stimulate the expression of factors involved in mitochondrial biogenesis, respiratory complexes I–IV, and FA oxidation." (PMID 32708786, 2020). "PPARγ acts as a receptor for molecules with anti-diabetic properties and is also capable of modulating adipogenesis; thus, plant extracts as well as single compounds are assayed for their PPARγ binding activity to screen those with a potential role in controlling diabetes." (PMID 32878147, 2020). "Ether lipids have also been identified as potential endogenous ligands of peroxisome proliferator-activated receptor gamma (PPARγ), a nuclear receptor critical for adipose tissue development and lipid metabolism, which is the target of the glitazone family of diabetes drugs." (PMID 28523433, 2018). "Notably, PPARγ agonists are commercially available treatments for Type 2 Diabetes Mellitus and may offer a potential therapeutic agent to aid in the treatment of inflammatory airways diseases." (PMID 30114278, 2018). "However, although PPARγ is associated with IR and type II diabetes, the 12Ala allele does not reduce the risk of diabetes in South Asians, Chinese, and Malaysians." (PMID 28042289, 2016). "The considerable host of actions performed by PPARG can be compared to those of vitamin D and VDR, which has been implicated in neurologic disorders, autoimmune pathologies, cardiovascular disease, diabetes mellitus, psoriasis or infectious disease, and, above all of what is mentioned, cancer." (PMID 27579030, 2016).
diabetes (continued). "PPARγ was first demonstrated as having the function of regulating adipocyte differentiation, metabolism, and glucose homeostasis; for this reason, PPARγ agonist is identified as a candidate in diabetes mellitus treatment, such as troglitazone, rosiglitazone, and pioglitazone." (PMID 25889216, 2015). "In conclusion, the present study investigated a PPARγ antagonist, and the results provide a new understanding and research basis for the future investigation into novel small molecular compounds with fewer side-effects for the treatment of type 2 diabetes mellitus." (PMID 25574213, 2015). "Hence EGFR blockade may hold promise, not only in limiting tubulointerstitial pathology in diabetic nephropathy, but also in limiting the sodium and water retention observed in patients with diabetes and exacerbated by PPARγ agonists." (PMID 23533381, 2013). "This new generation PPARγ sparing insulin sensitizer may provide an initial tool for relieving inherent human islet insulin signaling pathway resistance that is necessary to preserve the β-cell phenotype during β-cell expansion for the treatment of diabetes." (PMID 23650507, 2013). "Clinical trials have only shown modest effects of PPARα (fibrates) and PPARγ (thiazolidinediones and pioglitazone) agonists in reversing ART lipoatrophy, while other studies suggested these drugs may be useful in treating ART-associated diabetes and NAFLD." (PMID 23641933, 2013). "We hypothesize that E-M uncoupling in diabetes is due in part to increased level of homocysteine causing activation of latent MMP-9, attenuation of thioredoxin and TIMP-4 in response to antagonizing PPARγ." (PMID 20828387, 2010). "PPARγ and PPARα have similar antidiabetic and renoprotectiveeffects, therefore administration of PPARα or PPARα/γ dual agonists may be alsouseful for the prevention of kidney complications of type 1 as well as type 2diabetes mellitus." (PMID 19283081, 2008). "We found 15 SNPs in or near PPARG, but none were associated with diabetes." (PMID 17903298, 2007). "In summary, we found that modulating the PPARγ pathway increases NECTIN4 expression, which we leveraged by repurposing a diabetes drug, rosiglitazone, to increase targeting and anti-tumor efficacy of NECTIN4-CAR T cells." (PMID 40931013, 2025). "In diabetes mellitus, these signals can be dysregulated via one or several of the proteins driving insulin signaling (AKT1, PIK3R1, INSR, PPARG, and PIK3CG)." (PMID 41011980, 2025). "PPARγ agonists, such as thiazolidinediones (TZD), act as insulin-sensitizing agents and are currently used in clinical practice for the treatment of diabetes." (PMID 38892571, 2024). "Obesity and diabetes are accompanied by elevated inflammatory factors, such as TNF-α, which promote oxidative stress and reduce PPARγ expression." (PMID 39867658, 2024). "The results offer us a comprehensive understanding of the therapeutic effects of previously identified target proteins, including AKT1, IL6, PPARG, JUN, CASP3, EGFR, and PTGS2, in the context of diabetes intervention." (PMID 39707185, 2024). "Thiazolidinediones, a type of PPARγ agonist, are used to treat type 2 diabetes mellitus (T2DM) because its effect of promoting insulin sensitization, suggesting that PPARγ activation is beneficial to ameliorate diabetic cardiomyopathy." (PMID 38596692, 2024). "Our results revealed the interaction of FXN and PPARγ signaling pathway, shedding light on a pharmaceutical strategy for a positive feedback development in treating FRDA, beneficial from both diabetes and neurodegeneration." (PMID 39191875, 2024). "Gut microbiota metabolites primarily exert their therapeutic effects on diabetes through the IL6, AKT1, and PPARG targets." (PMID 39707185, 2024). "Considering the therapeutic potential of PPARγ agonists, which are FDA-approved for Type 2 Diabetes Mellitus, it becomes evident that these agents hold promise for preeclampsia treatment, particularly in patients with risk factors such as hyperglycemia." (PMID 37299422, 2023).